ALB (albumin)
Diseases named in the same sentence as ALB in open-access papers (continued):
Sharing a sentence is not in itself a finding about the gene and the disease.
liver disease (continued). "In the context of liver disease, where edema formation is predominantly due to decreased oncotic pressure from reduced albumin synthesis, the standard treatment involving spironolactone and loop diuretics was often effective." (PMID 39099956, 2024). "Contraindications involve patients with a history of hypersensitivity to natural or recombinant IFN-β, human albumin or any of the excipients, current severe depression and/or suicidal ideation, and decompensated liver disease." (PMID 38275058, 2024). "It is known thatwhile ALB level decreases in liver diseases, ALT and AST enzyme levelsincrease in liver diseases." (PMID 37033818, 2023). "The combination of albumin and vasopressors is a treatment of choice for HRS-AKI, according to the American association for the study of liver disease (AASLD) and European society for liver disease." (PMID 37510105, 2023). "Albumin is the most abundant plasma protein produced by the hepatic parenchymal cells, and lower albumin levels are correlated with liver disease." (PMID 37274322, 2023). "Because the two arms differed in terms of serum albumin, bilirubin, and platelet levels; the lymphocyte count; and radiological signs of portal hypertension, a propensity score was also used to analyse the primary outcome (liver PFS)." (PMID 36937990, 2023). "Decreased levels of ALB were the only observation consistent with liver disease and are also suggestive of increased vascular permeability associated with DIC." (PMID 36992478, 2023). "A strong negative correlation was seen with albumin levels (R = −0.642, p = 0.007), confirming that lower albumin is an indicator of more advanced liver disease." (PMID 37999215, 2023). "Intravascular volume overload can occur with excessive infusion of albumin, which can lead to cardiovascular instability, so patients with decompensated liver cirrhosis and portal hypertension need careful monitoring while on albumin." (PMID 37680416, 2023). "Human serum albumin (HSA) infusion serves an important role in the treatment of advanced liver disease." (PMID 37013893, 2023). "The combination of albumin and vasoconstrictors is the most important treatment for hepatorenal syndrome and can effectively improve the renal function." (PMID 37009616, 2023). "Laboratory values indicated that the post‐SVR/HCC group had a higher median MELD score, higher AST/ALT ratio, higher total bilirubin, lower albumin, and lower platelet counts, reflecting more advanced liver disease." (PMID 37078924, 2023). "The Child–Pugh score and model for end‐stage liver disease scores are conventionally used for estimating liver decompensation, although the alternatively developed albumin‐bilirubin score shows superior performance for predicting hepatic dysfunction." (PMID 37927928, 2023). "PRO-C3 was assessed in serum at baseline in cohorts 1 and 2, and compared with model for end-stage liver disease and albumin–bilirubin (ALBI) scores." (PMID 37284140, 2023). "In liver disease, HCC, due to the loss of albumin, the indole and phenol lose their binding ability and cannot break down." (PMID 37967076, 2023). "As part of screening for liver disease, serum aminotransferases, total proteins, and albumin are considered to be the most common liver function tests." (PMID 37004609, 2023). "Other factors related to the outcome of LT were MELD score and donor age for primary graft survival, recipient age ≥ 60 years, hepatorenal syndrome, pretransplant albumin for overall patient survival." (PMID 37550392, 2023). "Hepatic decompensation includes development of clinically overt ascites or hepatic hydrothorax related to portal hypertension (as suggested by a serum ascites albumin gradient [SAAG] > 1.1 g/dL)." (PMID 37358642, 2023). "Serum ascites albumin gradient scorewas calculated as 1.1 with 96.7% accuracy of correctly predicting that the asciteswas due to portal hypertension." (PMID 36691914, 2023).
liver disease (continued). "We confirmed the presence of several indicators for liver disease in AH patients: reduced serum albumin, enhanced serum total bilirubin, and enhanced INR." (PMID 37400491, 2023). "For instance, analysis of albumin functionality using the EPR method in patients with diverse liver diseases demonstrated a significant reduction in detoxification efficiency (DTE) compared to the control group." (PMID 37628734, 2023). "The serum albumin level is regarded as an important indicator of hepatic function, especially in patients with liver disease, because albumin is synthesized in the liver." (PMID 37167307, 2023). "We evaluated the covariates of age, height, sex, feeding status, AST, ALT, albumin, total bilirubin, DM, advanced age (≥60, ≥65, and ≥70 years old), renal disease, and liver disease." (PMID 37305528, 2023). "Similar to ALB, the serum concentration of pre-albumin is related to nutritional intake, inflammatory state, liver disease, endocrine disease, etc." (PMID 37089594, 2023). "In the univariate analysis, there was a significant difference in male sex, CURB score (2 < or =), multi-lobar chest X-ray involvement, albumin (per 1 g/dl), liver disease, kidney disease and use of antipsychotics between two groups." (PMID 37718411, 2023). "Because plasma proteins, particularly albumin (Alb), are predominantly synthesized in the liver, the significant drop in serum total protein also indicated liver disease." (PMID 37189698, 2023). "Analysis of zinc and albumin levels before zinc preparation treatment as covariates showed that the presence of liver disease contributed to an increase in zinc per 100 mg/day zinc preparation, with a significant difference (P = .0029)." (PMID 36701704, 2023). "In a retrospective study, 60 patients with hepatorenal syndrome were given midodrine, octreotide, and albumin, while 21 received only albumin." (PMID 37680416, 2023). "For example, patients with liver disease have a reduction in albumin synthesis due to a reduction in hepatocyte mass, resulting low serum albumin scores." (PMID 36848404, 2023). "Various medications, such as octreotide, midodrine, and dopamine, in conjunction with albumin, have been employed in attempts to manage hepatorenal syndrome." (PMID 37873544, 2023). "Because the two arms differed in terms of serum albumin, bilirubin, and platelet levels; the lymphocyte count; and radiologic signs of portal hypertension, a propensity score was also used to analyse the primary outcome (liver PFS)." (PMID 36937990, 2023). "The changing serum levels of albumin thus provide valuable evidence of acuteness, progression, and prognosis in liver disease." (PMID 36677938, 2023). "Vasoconstrictor therapy (specially terlipressin) and volume expansion (with albumin) is the recommended treatment of choice for the hepatorenal syndrome (HRS)-AKI to counteract systemic arterial vasodilation and hypovolemia." (PMID 35365736, 2022). "Cirrhotic ascites fluid is a transudative ascites due to portal hypertension with a serum–ascites albumin gradient (SAAG) ≥ 11 g/L." (PMID 35745058, 2022). "The perturbation in the specific hepatic enzymes like ALP, SGPT, SGOT, GGT, bilirubin, and albumin in peripheral blood is indicative of hepatocyte death, and hence is a useful marker of hepatic disease severity." (PMID 36405584, 2022). "Albumin and prothrombin concentrations decreased significantly through the progression of liver disease among the HCC group." (PMID 35651814, 2022). "As an early indicator of hepatic disease in marine mammals, the use of albumin is limited since it appears that these have a tremendous reserve capacity for hepatic albumin production." (PMID 36303601, 2022). "This should especially be considered in pathologies where plasma albumin is low (e.g., nephrotic syndrome, hepatic disease) or where albumin binding is impaired (e.g., uremic syndrome)." (PMID 36355090, 2022).
liver disease (continued). "Recent studies found compromised quality and impaired function of albumin in patients with liver diseases." (PMID 35769376, 2022). "Abdominal paracentesis was carried out, showing abundant citrine ascitic fluid with a serum‐ascites albumin gradient greater than 1.1 g/dl suggesting non‐infected cheliform transudate in favour of portal hypertension." (PMID 35822090, 2022). "EN-identified predictors included male sex, treatment < 8 weeks, treatment discontinuation due to adverse events, albumin level < 3.5 g/dL, total bilirubin level > 1.2 g/dL, advanced liver disease, and use of tobacco, alcohol, or vitamins." (PMID 36302828, 2022). "The higher number of patients with HCC history and lower levels of hemoglobin, platelet count, and serum albumin in the 12-week group relative to the 8-week group suggest a higher severity of liver disease in this group." (PMID 35980912, 2022). "Albumin administration also benefits cirrhotic patients with hepatorenal syndrome and can reduce their systemic inflammation and immune suppression." (PMID 35268297, 2022). "Paracentesis demonstrated a high serum-ascites albumin gradient with low total protein consistent with portal hypertension." (PMID 36060394, 2022). "Albumin has multiple functions and plays important roles in liver disease severity, progression, and prognosis." (PMID 35297102, 2022). "Analysis of liquid from abdominal paracentesis shows serum‐ascites albumin gradient greater than 1.1 g/dl, further supporting portal hypertension after exclusion of a cardiac involvement." (PMID 35822090, 2022). "Other serious liver diseases (e.g. acute liver failer) dramatically reduce the liver ability to remove waste products such as albumin, leading to further damages in patients." (PMID 34986721, 2022). "In this regard, a recent report showed that a low Fisher’s ratio correlated with the reduction in synthetic function of the liver, mainly albumin, and considered it as a good prognostic factor of liver disease." (PMID 36548692, 2022). "For instance, ALB is a protein produced by liver, which is widely used as a marker for liver diseases." (PMID 35196362, 2022). "Univariate analyses showed that multiple tumor numbers, low PLT (< 100 × 10^9/L), decreased ALB (< 35 g/L), portal hypertension, low PNI (< 48.48), and high GGT/ALT ratio (≥ 1.65) were associated with poor OS." (PMID 36132141, 2022). "The impact of liver disease severity just prior to LT in our patients was less obvious since bilirubin and albumin concentration, PELD, and post-operative days spent in PICU did not correlate with long-term FSIQ or the quality of life at the follow-up clinic." (PMID 38994390, 2022). "While one cluster focuses on functional parameters such as bilirubin, PT according to Quick (INR), cholinesterase and albumin, another primarily looks at indicators of toxic cell damage or liver disease that has already occurred." (PMID 35501826, 2022). "Patients with AIH had higher TB, AST, ALT, LDH, and IgG levels and lower albumin levels than those with other liver diseases." (PMID 35610317, 2022). "Rapamycin monotherapy proved ameliorative on both liver and spleen in cases of splenomegaly secondary to portal hypertension, but less improvement was observed regarding serum albumin level." (PMID 35949314, 2022). "The ratio of oxidized albumin to total albumin can increase in liver disease, DM, and cardiovascular disease—leading to bacterial or viral infections." (PMID 34638659, 2021). "The relationship between liver diseases and serum ALB redox state has well been documented for the last few decades." (PMID 33804859, 2021). "Before zinc supplementation, serum albumin levels, which generally predict the overall survival of patients with liver diseases, correlated with serum zinc levels of patients with AIH in this study (p < 0.05)." (PMID 34199421, 2021).
liver disease (continued). "The albumin-bilirubin (ALBI) score, which is calculated from the patient’s serum albumin and total bilirubin, has been proposed for assessing liver function and subsequent long-term mortality in patients with liver disease." (PMID 34830658, 2021). "Liver function tests, i.e. aspartate aminotransferase (AST), alanine transaminase (ALT), albumin, and bilirubin, along with clinical signs of liver disease chronicity, were noted." (PMID 33996337, 2021). "As seen in studies of liver diseases, serum ALB obtained from CKD patients induced neutrophil oxidative burst." (PMID 33804859, 2021). "The posttranslational modification of the cysteine residue at position 34 (34Cys), the only unpaired cysteine residue in the albumin molecule, can be used to monitor the severity of renal and liver disorders." (PMID 33810483, 2021). "Upon matching, there were no significant discrepancies between groups regarding gender distribution, liver disease etiology, laboratory workup (bilirubin, albumin, INR), decompensation history or concomitant decompensating events." (PMID 34441984, 2021). "In 53 (60.2%) cases, physicians reported hepatorenal syndrome (HRS-AKI) to be an indication for albumin treatment." (PMID 33270161, 2021). "Treatment with albumin also counteracts the development of hepatorenal syndrome and spontaneous bacterial peritonitis." (PMID 34836265, 2021). "The majority of specialists indicated using albumin at the recommended doses for hepatorenal syndrome (HRS-AKI, 86.4%) and for large volume paracentesis (LVP, 73.3%)." (PMID 33270161, 2021). "Albumin is used to evaluate the liver’s biosynthetic activity and capability, and the hepatic synthesis of albumin will decrease in end-stage liver diseases." (PMID 35154598, 2021). "Oxidized shifts of serum ALB redox state have been confirmed in oxidative stress-related diseases such as liver diseases and renal failure, and ALB redox state has, therefore, been viewed as an oxidative stress marker." (PMID 34067270, 2021). "Currently, international consensus recommends albumin for all cirrhotic patients with spontaneous bacterial peritonitis and hepatorenal syndrome to reduce mortality and improve renal function." (PMID 34670501, 2021). "The poisoned horses showed higher levels of globulins and decreased albumin, both of which indicate hepatic disease." (PMID 35097039, 2021). "We observed a correlation of HSA characteristics such as FA and bilirubin content, redox state, and the severity of liver disease with the conformation of albumin." (PMID 34127764, 2021). "The content of ALB reflects the liver function and the immune system status and has been used to diagnose liver diseases and lesions." (PMID 33435531, 2021). "Decreased albumin concentration and coagulopathy with prothrombin time prolongation or thrombocytopenia (due to hypersplenism and portal hypertension) usually occur when the end-stage liver disease develops." (PMID 34768617, 2021). "Although there is generally a good knowledge on the management of portal hypertension and use of albumin, there are also areas in which reported practice deviated from the national evidence-based recommendations." (PMID 33270161, 2021). "Patients with severe liver diseases usually have a lower concentration of albumin, which plays an important role in the clinical evaluation of liver function and is used as a diagnostic biomarker in the management of NAFLD." (PMID 35174195, 2021). "The Child-Pugh score is a system determined by scoring five clinical measures such as total bilirubin, serum albumin, prothrombin time, ascites, and hepatic encephalopathy for evaluating the prognosis of liver disease." (PMID 32339207, 2020). "Data showed that MSC therapy significantly improves liver function in patients with liver disease when analyzing the model of end-stage liver disease score, albumin, alanine aminotransferase, and total bilirubin levels, and prothrombin time." (PMID 33383629, 2020).
liver disease (continued). "The ALBI grade means a grading system with a combined serum albumin level and bilirubin level in patients with liver diseases; it has been introduced as a prognostic system alternative to the Child–Pugh classification system." (PMID 32456292, 2020). "Patients with low baseline serum albumin, taking other hepatotoxic drugs and having preexisting liver disease should be followed with serial liver enzymes after initiation of anti-tuberculosis medications." (PMID 33170847, 2020). "Compared to untreated patients, LES-treated patients had significantly more advanced liver disease in terms of laboratory variables (albumin, sodium, INR, and platelet count) and liver function (Child–Pugh score and class and MELD score)." (PMID 32260139, 2020). "Higher concentrations of ALP and γ-GT are indicators of liver disease, whereas a decrease in total proteins and albumin is indicative of chronic liver disease or abnormal excretion in some nephropathies." (PMID 33182225, 2020). "Liver-specific Pten-knockout mice (Ptenflox/flox: Albumin-Cre; Pten-Alb mice) are liver disease models used to develop steatosis, nonalcoholic steatohepatitis (NASH) and liver cancers stepwise." (PMID 33375248, 2020). "Low albumin levels can be seen in a number of serious conditions, such as like cancer, major infections, liver disease and inflammatory diseases, but can also indicate a poor nutritional status." (PMID 33152050, 2020). "Considering patients with liver disease, the BMI and the albumin level were significantly (and blood glucose nearly significantly) higher in the NAFLD than in the HCV subgroup, while the reverse was true for AST and ALT measures (also for p values)." (PMID 32910431, 2020). "Serum-ascites albumin gradient (SAAG) remains the most sensitive and specific marker for the differentiation of ascites due to portal hypertension from ascites due to other causes." (PMID 32437441, 2020). "The treatments for hepatorenal syndrome (HRS) were albumin plus a vasoconstrictor vs a vasoconstrictor alone." (PMID 31278624, 2019). "The more, so since the ascitic fluid volume is generally dependent on the degree of portal hypertension and serum albumin." (PMID 31781297, 2019). "Serum ALB levels can reflect liver reserve, especially synthetic function, which is parallel to the severity of liver disease." (PMID 31810204, 2019). "High albumin level reflected better nutrition status, liver function and immune response and indicated better outcomes in liver disease." (PMID 31612101, 2019). "Only 19 patients (4.7%) harbored a rs56163822 T‐allele and had less pronounced liver disease as indicated by lower Child–Pugh score (CPS, 6 ± 1 vs 7 ± 2 points, P = 0.034) and higher albumin levels (38.9 ± 4.9 vs 35.9 ± 5.9 g/L, P = 0.026)." (PMID 31062417, 2019). "Various groups confirmed the presence of IgG, IgM, and IgA antibodies against albumin in patients with liver disease." (PMID 30930689, 2019). "For example, it is well established that albumin infusion improves outcome of patients with septic shock, liver cirrhosis with hepatorenal syndrome or spontaneous bacterial peritonitis." (PMID 31068202, 2019). "Previous reports showed that platelet count, albumin level, and decreased portal flow velocity were associated with the risk of thrombotic events after treatment with TPO-RAs in patients with liver diseases." (PMID 30105510, 2019). "In advanced liver disease, the level of the serum ALB, which is a major protein produced by the liver, is reduced." (PMID 29747694, 2018). "As expected, patients with advanced fibrosis had a higher INR and lower albumin and thrombocytes, reflecting the severity of their liver disease." (PMID 30106985, 2018). "In chronically affected patients, the liver enzyme levels such as ALT, AST and albumin levels were higher compared to those with advanced liver diseases (LC, HCC) (P < 0.001)." (PMID 30419833, 2018).